NCOR2 (nuclear receptor corepressor 2)
Diseases named in the same sentence as NCOR2 in open-access papers (continued):
Sharing a sentence is not in itself a finding about the gene and the disease.
neuroblastoma (7 papers, 2012 to 2024). Neuroblastoma (NB) is the most common solid, extracranial childhood tumor. "In neuroblastoma cells, retinoic acid treatment induces the expression of miR-10a, which targets nuclear receptor corepressor 2 (NCOR2)." (PMID 36555120, 2022). "For example, miR-10a/b promotes the differentiation of cells from a type of nerve cell tumor (i.e., neuroblastoma cells) by suppressing translation of a protein called nuclear receptor corepressor-2 (NCOR2)." (PMID 24313161, 2013). "Other validated mRNA targets of miR-10b include KLF4 in human oesophageal cancer cell lines and the nuclear receptor co-repressor 2 (NCOR2) in neuroblastomas." (PMID 23125021, 2012). "The down-regulation of NCOR2 promotes the growth and differentiation of the neuroblastoma cells." (PMID 36555120, 2022). "Likewise, miR-10a and miR-10b are potent inducers of neuroblastoma cell differentiation through targeting of nuclear receptor corepressor 2 (NCOR2)." (PMID 25338081, 2014). "Thus, miR-10a/b promote neuroblastoma differentiation by suppressing NCOR2 expression." (PMID 23696417, 2013). "Moreover, miRNAs contribute to retinoic acid induced differentiation in neuroblastoma: miR-10a and miR-10b play a key role in neural cell differentiation through direct targeting of nuclear receptor corepressor 2 and concomitant downregulation of MYCN, a potent oncoprotein in neuroblastoma." (PMID 23503168, 2013).
ovarian carcinoma (7 papers, 2020 to 2025). A malignant neoplasm originating from the surface ovarian epithelium. "The identification of NCOR2 as one of the top eight genes responding to combination therapy in ovarian cancer is significant because like BDP1, NCOR2 contains a SANT domain." (PMID 36305848, 2023). "NCOR2 expression was evaluated by immunohistochemistry in a cohort of 156 epithelial ovarian cancer (EOC) tumor samples and correlated with GPER expression." (PMID 37131060, 2023). "The identification of NCOR2 as one of the top eight genes responding to combination therapy in ovarian cancer is significant because like BDP1, NCOR2 contains a SANT domain (SWI3, ADA2, N‐Cor, and yeast TFIIIB BDP1 proteins) (reviewed in17)." (PMID 36305848, 2023). "Hence, the frequency and hotspot mutations in the genes NCOR2, CIITA, MUC4, and MUC16 point towards their role in driving oncogenesis in all ovarian cancer histotypes." (PMID 37091785, 2023). "Accordingly, NCOR2 expression was found in more than 70% of ovarian cancers." (PMID 37131060, 2023). "The present study aims to investigate whether the expression of the nuclear co-repressor NCOR2 plays a role in GPER signaling which thereby could positively impact overall survival rates of ovarian cancer patients." (PMID 37131060, 2023). "In larger cohort studies of ovarian cancer transcriptomes showed NCOR2 as a biomarker for resistance; lower expression observed in the Indian Cohort might be a good predictor of chemotherapy response." (PMID 37091785, 2023). "Accordingly, the current study might serve as a potential starting point to further explore the complex molecular implications of the epigenetic regulator NCOR2 and its components on processes involved in ovarian cancer development, such as GPER-mediated signaling pathways." (PMID 37131060, 2023). "Altogether, these findings indicate that MMP14, a zinc (Zn2+)‐dependent endopeptidase, and NCOR2, a transcriptional corepressor, are additional promising candidate targets of the autoantibodies from our original study and may become accessible to circulating ligands in ovarian cancer." (PMID 40985572, 2025). "An amplification predicted to form a NCOR2-SCARB1 fusion gene was identified in one lung cancer cell line, CCDC6-ANK3-forming amplifications were found in two ovarian cancer cell lines, and a LHFPL3-KMT2E-forming amplification was found in one lung cancer." (PMID 33097743, 2020). "Since subtype-specific impact of NCOR2 expression on overall survival by Kaplan–Meier estimates was not statistically significant, the present study further evaluated general molecular mechanisms of ovarian cancer biology rather than focusing on subtype-specific analyses." (PMID 37131060, 2023).
Insulin resistance (6 papers, 2019 to 2025). Increased resistance towards insulin, that is, diminished effectiveness of insulin in reducing blood glucose levels. "The current study explored the miR-10a/b-5p-NCOR2 pathway in estrogen-deficient diabetic female mice, uncovering a gender-specific molecular mechanism of insulin resistance." (PMID 39337631, 2024). "A recent study has demonstrated estrogen-mediated protection against insulin resistance in females through the miR-10a/b-5p-NCOR2 axis, both in mice and humans." (PMID 39932930, 2025). "Research indicates that estrogen may reduce insulin resistance through the miR-10a/b-5p/NCOR2 pathway, inhibit the release of pro-inflammatory cytokines to regulate immune responses, and play a neuroprotective role." (PMID 40395813, 2025). "Notably, our findings underscore that in female T2D cases, characterized by insulin resistance, the pathogenesis is mainly driven through the miR-10a/b-5p-NCOR2-INSR axis." (PMID 39337631, 2024). "Elevated NCOR2 levels increase insulin (INS) production, which subsequently decreases INSR expression and AKT phosphorylation (p-AKT), leading to the development of insulin resistance and ultimately hyperglycemia." (PMID 39337631, 2024).
lung adenocarcinoma (6 papers, 2019 to 2023). A carcinoma that arises from the lung and is characterized by the presence of malignant glandular epithelial cells. "MTT results showed that the cell viability increased and apoptosis decreased after NCOR2 was knocked down in A549 cell line, which suggested that the decrease of NCOR2 may be the cause of cisplatin resistance in lung adenocarcinoma." (PMID 32508530, 2020). "High expression of heterochromatin 1γ is associated with poor prognosis of lung adenocarcinoma and promotes proliferation, colony formation and migration of lung adenocarcinoma cells by directly inhibiting NCOR2 expression." (PMID 32508530, 2020). "Ubiquitin ligase CHAF1B leads to cisplatin resistance in lung adenocarcinoma cells by promoting NCOR2 ubiquitination degradation." (PMID 32508530, 2020). "Alam etal. demonstrated that CBX3/HP1γ promoted proliferation, colony formation, and migration in lung adenocarcinoma (LUAD) cells by directly repressing NCOR2 and ZBTB7A." (PMID 31375643, 2019). "Moreover, CBX3 facilitates the progression of lung adenocarcinoma by directly repressing NCOR2 and ZBTB7A expression." (PMID 34395271, 2021). "Combined with the protein chip and experimental results, it was confirmed that the low expression of NCOR2 in lung adenocarcinoma cells may be one of the reasons for cisplatin resistance in lung adenocarcinoma." (PMID 32508530, 2020). "Another recurrent case (n = 4) was found in stomach, esophageal and lung adenocarcinoma, where SCARB1, a high-density lipoprotein (HDL) receptor, was overexpressed through fusion with NCOR2 due to tandem duplications on chromosome 12q24." (PMID 33097743, 2020). "The histone reader protein HP1γ could modulate the epigenetic suppression of the transcription‐repressive regulators NCOR2 and ZBTB7A to activate the protumorigenic transcriptome in lung adenocarcinoma." (PMID 36504353, 2023). "Only NCOR2 and PPP5C met the following requirements: it is down-regulated by more than 1.5 times in A549/DDP, interacts with CHAF1B, has a ubiquitination site and is lowly expressed in lung adenocarcinoma." (PMID 32508530, 2020). "Therefore, our results support that ubiquitin ligase induces cisplatin resistance in lung adenocarcinoma by promoting substrate degradation, and ubiquitin ligases CHAF1B and NCOR2 can be considered as potential biomarkers for cisplatin sensitivity in lung adenocarcinoma." (PMID 32508530, 2020).
Obesity (6 papers, 2013 to 2023). Accumulation of substantial excess body fat. "Any deficiencies or dysregulations of NCoR1, NCoR2, and HDAC3 have been associated with metabolic diseases such as obesity, type 2 diabetes, and NAFLD." (PMID 37674539, 2023). "HDAC4 was further a strong candidate due to multiple affected CpG sites within the gene, and both HDAC4 and NCOR2 are biologically interesting candidates in adipose tissue and the pathogenesis of obesity and type 2 diabetes." (PMID 23825961, 2013). "When we investigated the list of 162 DMRs mapping to annotated loci in further detail we observed other genes with known and potential roles in obesity and related traits (such as PRKCZ, NDUFS2, GATA2, FOXP2, ANGPT2, NCOR2, CPT1B, PTPN6)." (PMID 25651499, 2015).
type 2 diabetes (5 papers, 2013 to 2024). "Recent studies indicated that NCOR2 was involved in multiple disorders ranging from metabolic diseases such as type 2 diabetes to carcinogenesis." (PMID 32550907, 2020).
acute promyelocytic leukemia (4 papers, 2009 to 2025). An aggressive form of acute myeloid leukemia (AML), characterized by arrest of leukocyte differentiation at the promyelocyte stage, due to a specific chromosomal translocation t(15;17) in myeloid cells. "Well-established oncogenic roles for NCOR1 and NCOR2/SMRT have been elucidated in acute promyelocytic leukemia that results from a fusion between RARα, and either the promyelocytic leukemia (PML) or promyelocytic leukemia zinc finger (PLZF) genes." (PMID 23098689, 2013). "In acute promyelocytic leukemia, the promyelocytic leukemia–retinoic acid receptor (RAR)α fusion protein binds the corepressor NCOR2 with abnormally high affinity, thereby repressing differentiation genes even in the presence of physiological levels of the RARα ligand all trans retinoic acid." (PMID 41150850, 2025).
glioblastoma (4 papers, 2013 to 2024). The most malignant astrocytic tumor (WHO grade IV). "Reduced expression of SRSFs induces alternative splicing isoform switches of related oncogenes, such as BCL-XS and NCOR2, promoting glioblastoma multiforme (GBM) growth and progression." (PMID 33062255, 2020). "This process affects target mRNA alternative splicing, including BCL-X and nuclear receptor corepressor 2 (NCOR2), consequently contributing to the glioblastoma phenotype." (PMID 39342406, 2024).
glioma (4 papers, 2013 to 2025). A benign or malignant brain and spinal cord tumor that arises from glial cells (astrocytes, oligodendrocytes, ependymal cells). "Additionally, the strong nuclear expression of HDAC1, HDAC2, and NCOR2 in glioma cells, along with weak expression of NCOR1 and HDAC3, suggests a potential role for these proteins in tumor progression and as markers for patient prognosis." (PMID 40940748, 2025). "This proposes an important role of SMRT/NCOR2 in glioma tumors." (PMID 24244722, 2013). "Furthermore, previous reports also showed increased SMRT/NCOR2 expression in gliomas." (PMID 24244722, 2013). "In glioma cells, strong nuclear expression of HDAC1, HDAC2, and NCOR2 has been observed, while NCOR1 and HDAC3 show weaker expression." (PMID 40940748, 2025).
breast tumor (3 papers, 2009 to 2026). "Here, we show that nuclear corepressor 2 (NCOR2) is an epigenetic regulator of MHC class I molecule presentation on breast tumor cells." (PMID 42086546, 2026). "mRNA levels of NCOR2 and CITED2 in oestrogen receptor-positive breast tumours were determined by quantitative RT–PCR." (PMID 19904269, 2009).
cocaine dependence (3 papers, 2018 to 2025). A psychologically and socially impaired state, with or without physiological changes, that develops as a result of using cocaine and which leads to compulsive behaviors to acquire the substance. "SNPs in NCOR2 are associated with cocaine dependence in a recent GWAS." (PMID 30323833, 2018). "In humans, NCOR2 has been associated with cocaine dependence in European-Americans, although this association did not replicate in African-American populations." (PMID 41004526, 2025).
diabetes (3 papers, 2019 to 2025). "Additionally, 7 CpG sites annotated to MAN2A2, ABCG1, DENND3, NCOR2, BAIAP2 and CPT1A were linked to changes in diabetes status." (PMID 39827095, 2025). "Notably, among the seven CpG sites liked to the diabetes progression, five showed a negative correlation with gene expression levels, including cg23436042, cg11183227 (MAN2A2), cg06500161 (ABCG1), cg06710464 (BAIAP2), and cg17058475 (CPT1A), while cg08788930 (DENND3) and cg11311053 (NCOR2) did not." (PMID 39827095, 2025).
gastric cancer (3 papers, 2022 to 2025). A primary or metastatic malignant neoplasm involving the stomach. "Additionally, mutations in NCOR2 are linked to the occurrence of multiple gastric cancers." (PMID 41551593, 2025).
hepatocellular carcinoma (3 papers, 2020 to 2022). A malignant tumor that arises from hepatocytes. "MIR22HG was found to inhibit growth, migration and invasion through regulating the miR-10a-5p/NCOR2 axis in hepatocellular carcinoma cells." (PMID 32127004, 2020). "For instance, MIR22HG was down-regulated in hepatocellular carcinoma and its overexpression may affect miR-10a-5p/NCOR2 axis to suppress the invasion, migration and proliferation of cancer cells." (PMID 32500915, 2020).
leukemia (3 papers, 2013 to 2024). A malignant (clonal) hematologic disorder, involving hematopoietic stem cells and characterized by the presence of primitive or atypical myeloid or lymphoid cells in the bone marrow and the blood. "In addition to gene mutations that are known to be involved in leukemogenesis, such as ones in MYC and KRAS, we also identified mutations within PTPN21, TBX21, USP54, USP11, NCOR2, CSPP1 that have never before been identified in human leukemia." (PMID 26527318, 2016).
melanoma (3 papers, 2022 to 2025). A malignant, usually aggressive tumor composed of atypical, neoplastic melanocytes. "Nuclear receptor corepressor 2 rs2342924 T>C predicts SKCM prognosis, likely through Notch pathway mutations, that increase melanoma cell proliferation." (PMID 41479783, 2025).
bladder cancer (2 papers, 2013 to 2022). "Increased NCOR1 and NCOR2/SMRT expression occurs also in breast and bladder cancer and suppressed the responsiveness of nuclear receptors that exert mitotic restraint, such as VDR and PPARα,γ." (PMID 23098689, 2013).
bone neoplasm (2 papers, 2021 to 2022). A benign, intermediate, or malignant neoplasm involving the bone or articular cartilage. "This HMGA2::NCOR2 fusion has recently been described in a series of 6 “giant cell tumors of soft tissue” and in a series of 6 “osteoclastic giant cell-rich tumors of bone”." (PMID 36439507, 2022).
colorectal cancer (2 papers, 2018 to 2024). A primary or metastatic malignant neoplasm that affects the colon or rectum. "Protein factors that could regulate transcription of SMAD4-213 via AnnoLnc2 predicted binding sites upstream of/overlapping TSS that are expressed in colorectal cancer are CDX2, CEBPB, ELF1, NCOA1, NCOR1, NCOR2 and TFAP4." (PMID 39132157, 2024).
giant cell tumor (2 papers, 2022). A benign, intermediate, or malignant tumor that arises from the bone or soft tissue. "RNA-seq led to the reclassification of four “HMGA2::NCOR2 giant cell tumors”." (PMID 36439507, 2022).
head and neck squamous cell carcinoma (2 papers, 2018 to 2021). A squamous cell carcinoma that arises from any of the following anatomic sites: lip and oral cavity, nasal cavity, paranasal sinuses, pharynx, larynx, and salivary glands. "In support of our results, a number of studies have demonstrated a tumour suppressive role of NCOR2 in cancers, such as LUAD, head and neck squamous cell carcinoma, non-Hodgkin lymphoma and osteosarcoma." (PMID 34145290, 2021).
memory impairment (2 papers, 2021 to 2023). "A site within the intron of NCOR2, which regulates gene expression by activating histone deacetylase 3, and whose loss is associated with memory impairment, also showed nominally significant differential hydroxymethylation (p = 1.1 × 10−4)." (PMID 37139321, 2023). "Loss of Ncor2 function has been associated with memory impairment and reduced social interactions via altered GABAergic signaling in mice." (PMID 33407853, 2021).
mesenchymal tumor (2 papers, 2024 to 2025). "A case of GLI1-altered mesenchymal tumour with NCOR2(exon 1)::GLI1(exon 4) fusion has been reported, which showed no recurrent disease at 4 months follow-up." (PMID 41035732, 2025). "We report a rare case of a pleural-based GLI1-altered mesenchymal tumour with a previously undescribed NCOR2::GLI1 gene fusion and unusual SOX10 positivity in a young adult with synchronous colorectal adenocarcinoma." (PMID 41035732, 2025). "A pleural nodule was incidentally detected during staging, and biopsy revealed a mesenchymal tumour with a novel NCOR2(exon 7)::GLI1(exon 6) gene fusion." (PMID 41035732, 2025).
non-Hodgkin lymphoma (2 papers, 2018 to 2021). Distinct from Hodgkin lymphoma both morphologically and biologically, non-Hodgkin lymphoma (NHL) is characterized by the absence of Reed-Sternberg cells, can occur at any age, and usually presents as a localized or generalized lymphadenopathy associated with fever and weight loss. "For example, NCOR2 is downregulated in multiple myeloma and its low expression is associated with the development of non-Hodgkin’s lymphoma and poor prognosis of lung adenocarcinoma (LUAD) patients." (PMID 34145290, 2021).
preeclampsia (2 papers, 2014 to 2024). Preeclampsia is a hypertensive disorder of pregnancy that is characterized by new-onset hypertension with proteinuria presenting after 20 weeks of gestation, and depending on mild or severe forms may initially present with severe headache, visual disturbances, and hyperreflexia. "Currently, no literature has been found linking NCOR2 with preeclampsia." (PMID 39521940, 2024).
schizophrenia (2 papers, 2018 to 2021). A major psychotic disorder characterized by abnormalities in the perception or expression of reality. "Among the top candidate genes pinpointed by the analysis of the link between neuronal RG differentiation and schizophrenia are ZDHHC8, NCOR2 and CACNA1A, which were previously implicated as SCZ risk genes." (PMID 34194671, 2021). "In the network, candidate genes with nominal significance such as ANKS1B, CNTN2, CNTNAP2, GABBR2, NCOR2, and NTRK3 also may be involved in the pathology of schizophrenia." (PMID 30323833, 2018).
serous ovarian cancer (2 papers, 2023). "Taken together, this suggests that BDP1 is behaving similarly to an already established biomarker of serous ovarian cancer, NCOR2, in clinical samples treated with chemotherapies platin and taxane." (PMID 36305848, 2023). "For serous ovarian cancer patients, NCOR2 was identified as a possible predictive biomarker of chemotherapy response among seven other genes in a gene array study, correlating with resistance to chemotherapy." (PMID 37131060, 2023).
triple-negative breast carcinoma (2 papers, 2025 to 2026). An invasive breast carcinoma which is negative for expression of estrogen receptor (ER), progesterone receptor (PR), and human epidermal growth factor receptor 2 (HER2). "In triple-negative breast cancer (MDA-MB-231 and 4T1) cells, emodin targets nuclear receptor corepressor 2 (NCOR2) to upregulate seryl-tRNA synthetase (SerRS), suppressing VEGFA transcription and angiogenesis." (PMID 40490812, 2025).
abdominal aortic aneurysm (1 paper, 2026). Enlargement and ballooning of the vessel that supplies arterial blood to the abdomen, pelvis and legs. "While NCOR1 has already been linked to vascular biology, its relevance in abdominal aortic aneurysm (AAA) remains unclear, particularly for NCOR2." (PMID 42072455, 2026).
adenoma (1 paper, 2022). A neoplasm arising from the epithelium. "The results also included previously unreported genes including AKT3, NCOR2, PIK3R2, SMAD4, and TGFBR1, from which AKT3 and PIK3R2 were present in the early adenoma stage and SMAD4 and TGFBR1 were present at the late adenoma stage." (PMID 36499586, 2022).